CHEK2 (checkpoint kinase 2)
Diseases named in the same sentence as CHEK2 in open-access papers (continued):
Sharing a sentence is not in itself a finding about the gene and the disease.
breast cancer (continued). "Yet, given the variations in risk based on specific GPVs, such as the established differences in breast cancer risks for the CHEK2 1100delC GPV compared to the CHEK2 I157T GPV genotypes, it is important to account for these differences when estimating risks." (PMID 39062660, 2024). "PVs in genes with moderate penetrance, such as ATM, CHEK2, BRIP1, and PALB2, double the risk of breast cancer." (PMID 39624521, 2024). "Germline pathogenic variants (PVs) in ATM, BRCA1, BRCA2, CHEK2, and PALB2 are detected in 5-7% of unselected women with breast cancer in the general population and are associated with a significantly increased risk of breast cancer in unaffected women." (PMID 39624521, 2024). "While CHEK2 is generally categorized as a “moderate penetrance gene” for breast cancer, our study highlights the importance of considering cancer risk on a continuum based on the allele (GPV) rather than binary based on the gene." (PMID 39062660, 2024). "Other homologous recombination DNA damage repair (HR-DDR) genes associated with breast cancer risk accounted for 15.9% (13/82) of the carriers, including ATM (n = 2), BARD1 (n = 4), CHEK2 (n = 1), PALB2 (n = 2), RAD51C (n = 1), and RAD51D (n = 3)." (PMID 38893140, 2024). "We found that breast cancer susceptibility variants in BRCA1, BRCA2, ATM, and CHEK2 were associated with development of CBC in a subtype-specific manner." (PMID 39786405, 2024). "Specifically, PVs in PALB2, ATM, CHEK2, RAD51C, and RAD51D are associated with increased lifetime breast cancer risk, ranging from 20% to 58%, depending on the defective gene and identified variant, while influenced by family history." (PMID 39001430, 2024). "The study will enrol women, unaffected by cancer, undergoing predictive testing at a familial cancer clinic for a pathogenic variant in a known breast cancer (BC) or ovarian cancer (OC) predisposition gene (BRCA1, BRCA2, PALB2, CHEK2, ATM, RAD51C, RAD51D)." (PMID 39107016, 2024). "With ever-expanding familial databases and collaboration, further biomarkers in PALB2 and CHEK2 familial breast cancers should be explored, with some small case series showing some benefit of platinum-based chemotherapy in these cancers." (PMID 36831687, 2023). "Multi‐state model in all breast cancer patients and in patients diagnosed with a first primary ER‐positive breast cancer: hazard ratio for the comparison of CHEK2 c.1100delC carriers versus non‐carriers for each transition." (PMID 37401034, 2023). "In the unselected breast cancer cohort, twelve CHEK2 p.(Asp438Tyr) carriers were identified (12/2003, 0.6%, P = 0.66, OR = 0.78, 95% CI = 0.34–1.80)." (PMID 36653541, 2023). "For missense variants in aggregate, rare missense variants in specific domains in BRCA1, ATM, CHEK2, and PALB2 were significantly associated with increased risk of certain breast cancer subtypes." (PMID 37790698, 2023). "Five individuals had deletions of CHEK2 exons 9–10, characteristic of a 5395 bp deletion (del5395) estimated to account for 1% of breast cancers in Poland." (PMID 36797466, 2023). "The authors identified protein-truncating variants in BRCA1, BRCA2, CHEK2, PALB2 and ATM that were significantly associated with breast cancer risk." (PMID 37662839, 2023). "Recently, the Breast Cancer Consortium highlighted the necessity to also treat variant in other genes, including among others ATM, CHEK1, and CHEK2, in a similar manner to BRCA alterations, given their important influence on breast cancer development." (PMID 36753055, 2023). "Based on the mutation frequencies, the magnitude of cancer risk, and the influence on clinical management with mutation carriers, the most important breast cancer susceptibility genes include BRCA1, BRCA2, PALB2, and CHEK2." (PMID 37510234, 2023).
breast cancer (continued). "Proportions vary with ancestry, but an estimated 5–10% of breast cancer cases carry germline variants in genes associated with moderate to strong breast cancer risk (e.g., BRCA1, BRCA2, and CHEK2)." (PMID 37060015, 2023). "Based on our results, in Poland, we use a panel of founder mutations in BRCA1, BRCA2, CHEK2, and PALB2 as an initial screening tool for all patients with breast cancer and unaffected individuals with a positive family history of breast cancer." (PMID 37510234, 2023). "In this prospective review of 15,104 women with breast cancer with 11-year median follow-up, CBC was seen in 5.3%, with a significant increase in women with BRCA1, BRCA2, and CHEK2 mutations (p < 0.05)." (PMID 37232811, 2023). "Here we examined the impact of two traditional markers of hereditary cancer risk (age at breast cancer diagnosis and family cancer history) on the risk of carrying a PV in the most commonly mutated breast cancer-risk genes: ATM, BRCA1, BRCA2, CHEK2, and PALB2." (PMID 37084156, 2023). "The data presented here showed that the presence of familial breast cancer was more strongly associated with PV carrier status for ATM, BRCA1, BRCA2, CHEK2, and PALB2, in affected women (similar to previous studies)." (PMID 37084156, 2023). "We determined the functional consequences for the majority of CHEK2 missense VUS found in patients with breast cancer (3,660/4,436; 82.5%)." (PMID 37449874, 2023). "Distribution of VUS in breast cancer predisposing genes were :APC:1(5.8%), ATM:2(11.7%), BRCA1:1(5.8%), BRCA2:5(29.4%), BRIP1:1(5.8%), CDKN2A:1(5.8%), CHEK2:2(11.7%), FANC1:1(5.8%), MET:1(5.8%), STK11:1(5.8%), NF2:1(5.8%)." (PMID 37277882, 2023). "Several studies have examined the potential risk modification of SNP/SNVs in familial breast cancers and, in particular, BRCA1, BRAC2, CHEK2, PALB2 and ATM mutation carriers." (PMID 36831687, 2023). "Overall, these data suggest that germline mutations in CHEK2 contribute to the evolution of ER-driven, premenopausal ER+/HER2− breast cancer." (PMID 37390209, 2023). "Five variants were in genes which have been reported to be associated with breast cancer risk in at least 50 manuscripts in PubMed (DST, CHEK2, FASN, TNN, and PMS2)." (PMID 38136396, 2023). "We found a similar association between incidence of germline CHEK2 mutations and worse relapse-free survival in patients with primary ER+/HER2− breast cancer in METABRIC (HR = 6.15, P = 0.01)." (PMID 37390209, 2023). "Three of the CHEK2 p.(Asp438Tyr) carriers had additional breast cancer cases in their first- and/or second-degree relatives (Uns1-3) and three had other cancer types in their family (Uns3–5), but no samples from the relatives were available for testing." (PMID 36653541, 2023). "More recently, the largest WES study for overall breast cancer reported increased breast cancer risk associated with ATM, CHEK2, PALB2, and MSH6." (PMID 35884425, 2022). "The CHEK2 c.1100delC PV was identified in only 2/379 (0.53%) compared with 1.7% (55/3177) in women with breast cancer aged >30 years (p=0.0835) seen at the MCGM and 2.3% in the POSH study aged ≤40% and 1% in POSH cases≤30 years." (PMID 33758026, 2022).
breast cancer (continued). "These genes include “moderate penetrance” breast cancer susceptibility genes such as ATM and CHEK2, mutations in which are associated with a 2‐4‐fold increase in lifetime risk of female breast cancer." (PMID 36054727, 2022). "In our analyses of any 2+ primary cancers and our breast cancer-specific analysis, we replicated associations for known pleiotropic genes, BRCA2 (pLOF, p = 3.76 × 10−11 and 1.91 × 10−9) and CHEK2 (pLOF + missense, p = 2.95 × 10−11 and 1.67 × 10−8)." (PMID 36199081, 2022). "We report an intragenic CHEK2 duplication, ranging from intron 5 to intron 13, identified in an Italian family with hereditary breast cancer." (PMID 35885426, 2022). "In their study 60% (12/20) of PALB2 and 58% (7/12) of ATM/CHEK2 carriers with breast cancer underwent RRM compared to 57% (4/7) and 29% (2/7) of those without breast cancer, respectively." (PMID 36054727, 2022). "The current validation study successfully detected confirmed breast cancer susceptibility genes such as ATM, CHEK2, and PALB2." (PMID 35884425, 2022). "Our study design shows that we had the power to detect genes with effect sizes similar to some confirmed breast cancer susceptibility genes, such as ATM and CHEK2." (PMID 35884425, 2022). "For breast cancer, several genes such as BRCA1, BRCA2, PALB2, ATM, and CHEK2 act as high- to moderate-penetrance cancer susceptibility genes." (PMID 35853889, 2022). "Previous studies note an approximately 4% incidence of CHEK2 *1100delC truncation carriers among premenopausal breast cancer patients." (PMID 36011273, 2022). "Of 65 individuals with CHEK2, there were 50% with a family history of breast cancer, 34% with a family history of breast cancer at a young age at <age 50, 14.3% with a family history of ovarian cancer, and 21% with other HBOC‐related cancers in their families." (PMID 35040284, 2022). "The predicted proportion of breast cancer cases possessing pathogenic germline missense variants in these genes is approximately 0.6%, 0.3%, 0.2%, and 1.3% for ATM, BRCA1, BRCA2, and CHEK2, respectively." (PMID 35585550, 2022). "Targeted enrichment sequencing of the panel of 32 known or suspected breast cancer susceptibility genes confirmed the associations of known breast cancer susceptibility genes ATM, CHEK2, and PALB2." (PMID 35884425, 2022). "Based on the estimated overall risk for breast cancer protein-truncating variants, ATM, BRCA1, BRCA2, CHEK2 and PALB2 were identified as the major cancer susceptibility genes in the study population." (PMID 36568162, 2022). "Protein truncating variants in ATM, BRCA1, BRCA2, CHEK2, and PALB2 are associated with increased breast cancer risk, but risks associated with missense variants in these genes are uncertain." (PMID 35585550, 2022). "CHEK2 average cumulative breast cancer risks were even higher than expected from literature, but have large confidence intervals." (PMID 35938029, 2022).
breast cancer (continued). "As of September 2014, routine genetic testing for newly referred breast cancer patients in the Netherlands includes testing for the CHEK2 PV." (PMID 33468213, 2021). "In our cohort, ten out of fifty-two (19.2%) CHEK2 carriers were diagnosed with contralateral breast cancer, of whom one also developed colorectal cancer." (PMID 33925588, 2021). "Germline variants in ATM, BRCA1, BRCA2, CHEK2, and PALB2 were associated with a high risk of breast cancer; a more modest risk was associated with BARD1 and RAD51C." (PMID 34445631, 2021). "Among these, BRCA1, BRCA2, and PALB2 were still classified as high risk, and ATM, BARD1, CHEK2, and RAD51D were still classified as moderate risk breast cancer susceptibility genes in Chinese women." (PMID 34606182, 2021). "To address this knowledge gap, we conducted a genetic screen of CHEK2 in an Australian population-based case-control-family study of breast cancer." (PMID 33803639, 2021). "We estimated the prevalence of 20 alleles in six genes (BRCA1, BRCA2, CHEK2, PALB2, NBN, RECQL) in 165 Polish male breast cancer patients." (PMID 34461861, 2021). "In the current study, we evaluated the frequency of 20 recurrent mutations in six genes (BRCA1, BRCA2, CHEK2, PALB2, NBN and RECQL) in 165 men diagnosed with breast cancer in Poland." (PMID 34461861, 2021). "reviewed 715 male breast cancer patients who underwent germline multi-gene panel testing and found that pathogenic variants in CHEK2 (OR = 3.7, p = 6.24 × 10-24) and PALB2 (OR = 6.6, p = 0.01) were both significantly associated with breast cancer risk in men." (PMID 33959510, 2021). "A founder mutation of BRCA1, BRCA2, CHEK2, PALB2 and NBN was found in 13.3% of men with breast cancer in Poland." (PMID 34461861, 2021). "BARD1 (OR: 3.1, 95% CI: 1.3–7.2); CHEK2 (OR: 2.5, 95% CI:1.4–4.6); RAD51D (OR: 2.2, 95% CI: 1.3–3.8); and ATM (OR: 2.1, 95% CI: 1.2–3.6) were classified as moderate risk breast cancer risk genes." (PMID 34606182, 2021). "As for FBC, pathogenic mutations in other breast cancer genes have also been recently associated with an increased risk of MBC, such as PALB2 and CHEK2 mutations." (PMID 34298749, 2021). "Similar results were found through a screening of 65,057 white woman with breast cancer where a high or moderately increased risk of disease was found in relation with pathogenic mutations in ATM, CHEK2, PALB2, and RAD51D." (PMID 34299313, 2021). "Recently published guidelines offer recommendations on the management of breast cancer in patients with germline mutations in BRCA1/2, PALB2, CHEK2 and ATM." (PMID 34422626, 2021). "In the three Belgian patients, c.1100delC was identified; the Czech CHEK2 PV spectrum was more diverse, as recently reported in Czech breast cancer patients." (PMID 34503238, 2021).
breast cancer (continued). "A population-based study found the CHEK2/1100delC was present in 4.2% of unselected male breast cancer cases, more prevalent than the frequency of 1.1% in 1,692 controls (OR = 4.1, 95% CI: 1.2-14.3, p = 0.05)." (PMID 33959510, 2021). "This study classified ATM, BARD1, CHEK2, and RAD51D as moderate risk breast cancer susceptibility genes in Chinese women." (PMID 34606182, 2021). "Moderate penetrance breast cancer susceptibility gene mutations such as PALB2, CHEK2, ATM occur in 4-6% of breast cancer patients." (PMID 34422626, 2021). "Next, we did another follow-up using 45 CHEK2 carriers plus 87 familial breast cancer patients and 47 controls from the Swedish cohorts." (PMID 34285278, 2021). "We performed whole-exome sequencing in 28 breast cancer cases with germline CHEK2:c.1100delC, 28 familial breast cancer cases and 70 controls." (PMID 34285278, 2021). "With our approach we identified 66 carriers of the CHEK2 PV, of whom 64 had been previously diagnosed with breast cancer at a relatively young age (mean age at diagnosis was 49 years)." (PMID 33468213, 2021). "Although CHEK2 c.1100delC has been investigated in population-based studies of younger women with breast cancer, few have used methodologies that are demonstrated to provide unbiased estimates." (PMID 33803639, 2021). "For the clinical management of GPV carriers of ATM, CHEK2, or BARD1, all of which are autosomal dominant, it is recommended to perform imaging screenings for preventive risk management against breast cancer." (PMID 35008774, 2021). "ATM, BARD1, CHEK2, and RAD51D were associated with a moderate risk of breast cancer with ORs ranging from 2-fold to 4-fold." (PMID 34606182, 2021). "Herein, we illustrate the histopathological characteristics and clinical outcomes of 52 Greek breast cancer patients who are CHEK2 carriers." (PMID 33925588, 2021). "Overall, germline BRCA1 mutated cancers had significantly higher cyclin E1 protein than the BRCA1 wildtype cases, and tumors with other breast cancer associated germline mutations (BRCA2, PALB2, or CHEK2)." (PMID 34465787, 2021). "A quarter of ATM-related breast cancer and approximately one-third (30%) of CHEK2-related breast cancers were in situ carcinomas." (PMID 35008774, 2021). "Our study shows that mutations in the CHEK2 and PALB2 genes are important risk factors for male breast cancer in Poland." (PMID 34461861, 2021). "Upon further genetic testing, we identified co-existing germline CHEK2 and BRCA pathogenic variants in this family cluster with breast cancer; this represents a rare occurrence with only few reported cases." (PMID 33507482, 2021). "Both of these patients were diagnosed with bilateral breast cancer and both carried a mutation in the PALB2 gene.a- for BRCA1, CHEK2, PALB2, NBN mutation frequencies in cancer-free controls were from our previous studies." (PMID 34461861, 2021). "The vast majority (88.2%; 45/51) of female CHEK2 carriers were diagnosed with premenopausal breast cancer, with two thirds of them (60.8%; 31/51) being diagnosed at a young age, i.e., <45 years." (PMID 33925588, 2021). "In the breast cancer patients with the CHEK2 PV in our study, 91.7% had estrogen-receptor-positive cancer, 78.8% had progesterone-receptor-positive cancer and 68.8% had a negative epidermal growth factor receptor 2 (HER2)-status." (PMID 33468213, 2021).